ZNF511 (zinc finger protein 511)
Description:
May be involved in transcriptional regulation.
Synonyms: MGC30006; Zfp511
Tractability: No criterion of Open Targets' tractability assessment is met for any kind of drug.
Gene: Protein-coding gene on chromosome 10 (133,308,899 to 133,313,162, forward strand). Ensembl gene ENSG00000198546.
Subcellular location: Nucleus
Subcellular location (Human Protein Atlas): Nuclear bodies; Nucleoplasm; Vesicles
Gene Ontology:
Molecular function: protein binding; DNA-binding transcription factor activity
Biological process: regulation of DNA-templated transcription
Cellular component: nucleus
Genetic constraint (gnomAD): Loss-of-function variants: 28 observed, 27.82 expected, observed/expected ratio (o/e) 1.01, 90% interval 0.75 to 1.38. The upper end of that interval is the gene's LOEUF score, 1.38, which puts it in group 5 of 6, group 1 being the genes least tolerant of losing a copy. Missense variants: 358 observed, 336.97 expected, observed/expected ratio (o/e) 1.06, 90% interval 0.97 to 1.16. Synonymous variants: 144 observed, 134.06 expected, observed/expected ratio (o/e) 1.07, 90% interval 0.94 to 1.23.
Homologues: Orthologues: macaque ZNF511 (95% identical), chimpanzee ZNF511 (90% identical), guinea pig ZNF511 (75% identical), mouse Zfp511 (73% identical), dog ZNF511 (73% identical), pig ZNF511 (73% identical), rat Zfp511 (68% identical), zebrafish znf511 (46% identical), Drosophila melanogaster l(2)k10201 (24% identical).
Diseases named in the same sentence as ZNF511 in open-access papers:
ZNF511 is named in the same sentence as 3 diseases in open-access papers, as found by Europe PMC text mining. Sharing a sentence is not in itself a finding about the gene and the disease. The quoted sentences say what the papers report.
colon cancer (1 paper, 2022). "However, in the current state of the research, there are still many ZFPs whose mechanisms of action in colon cancer are not fully understood, and more mechanisms need to be further studied, such as ZNF146, ZNF511, ZNF346, ZNF638, ZNF700, and ZNF768." (PMID 36358661, 2022).
prostate carcinoma (1 paper, 2020). A carcinoma that arises from epithelial cells of the prostate gland. "In prostate cancer, we identified the transcript ENST00000361518 of Zink Finger Protein 511 (ZNF511) as a cMDT in all 19 PCAWG samples, while the 10 AA longer alternative transcript ENST00000359035 was found as MDT in normal prostate GTEx samples." (PMID 32879328, 2020).
ZNF511 also shares sentences with these, for which no sentence is quoted: cancer (2 papers).